COX16 (cytochrome c oxidase assembly factor COX16)
Description:
Required for the assembly of the mitochondrial respiratory chain complex IV (CIV), also known as cytochrome c oxidase. Promotes the insertion of copper into the active site of cytochrome c oxidase subunit II (MT-CO2/COX2). Interacts specifically with newly synthesized MT-CO2/COX and its copper center-forming metallochaperones SCO1, SCO2 and COA6. Probably facilitates MT-CO2/COX2 association with the MITRAC assembly intermediate containing MT-CO1/COX1, thereby participating in merging the MT-CO1/COX1 and MT-CO2/COX2 assembly lines.
Synonyms: hCOX16; C14orf112; HSPC203; MC4DN22
Tractability: Antibody: UniProt predicts a signal peptide or a membrane-spanning region. PROTAC: ubiquitination databases record sites on it; its protein half-life has been measured.
Gene: Protein-coding gene on chromosome 14 (70,325,081 to 70,416,984, reverse strand). Ensembl gene ENSG00000133983.
Subcellular location: Mitochondrion inner membrane
Subcellular location (Human Protein Atlas): Mitochondria
Pathways (Reactome):
Metabolism: Complex IV assembly
Gene Ontology:
Molecular function: protein binding
Biological process: mitochondrial respiratory chain complex IV assembly
Cellular component: mitochondrial inner membrane; mitochondrion; mitochondrial membrane
Genetic constraint (gnomAD): Loss-of-function variants: 12 observed, 14.15 expected, observed/expected ratio (o/e) 0.85, 90% interval 0.54 to 1.37. The upper end of that interval is the gene's LOEUF score, 1.37, which puts it in group 5 of 6, group 1 being the genes least tolerant of losing a copy. Missense variants: 124 observed, 124.01 expected, observed/expected ratio (o/e) 1, 90% interval 0.86 to 1.16. Synonymous variants: 46 observed, 40.04 expected, observed/expected ratio (o/e) 1.15, 90% interval 0.91 to 1.47.
Gene-disease validity (ClinGen):
ClinGen rates the evidence that COX16 causes each of these diseases.
mitochondrial disease (autosomal recessive): Moderate.
Homologues: Orthologues: chimpanzee COX16 (99% identical), guinea pig COX16 (91% identical), pig COX16 (91% identical), rabbit COX16 (87% identical), dog COX16 (85% identical), mouse Cox16 (85% identical), rat Cox16 (85% identical), tropical clawed frog cox16 (57% identical), zebrafish cox16 (55% identical). Paralogues in human: KIAA1614 (22% identical), SYNJ2BP (14% identical).
Diseases named in the same sentence as COX16 in open-access papers:
COX16 is named in the same sentence as 14 diseases in open-access papers, as found by Europe PMC text mining. Sharing a sentence is not in itself a finding about the gene and the disease. The quoted sentences say what the papers report.
breast carcinoma (5 papers, 2023 to 2025). "For Complex IV, the assembly factor COX16 was recently found in a fusion transcript (SYNJ2BP–COX16) that drives mitochondrial fragmentation, EMT, and metastatic progression in breast cancer cells." (PMID 41157129, 2025). "In breast cancer cells, SYNJ2BP-COX16 (a readthrough of synaptojanin 2 binding protein and COX16) SUMOylation regulates mitochondrial morphology through DRP1 SUMOylation and DRP1 phosphorylation at S616." (PMID 37627290, 2023).
Encephalopathy (1 paper, 2021). Encephalopathy is a term that means brain disease, damage, or malfunction. "In conclusion, this is the first report of two unrelated patients with a pathogenic variant in the COX16 gene responsible for the complex IV deficiency leading to neonatal hypertrophic cardiomyopathy, encephalopathy, and severe lactic acidosis with fatal outcome." (PMID 33169484, 2021).
hypertrophic cardiomyopathy (1 paper, 2021). A condition in which the myocardium is hypertrophied without an obvious cause. "In this report, we describe two unrelated patients with lactic acidosis, hypertrophic cardiomyopathy, and a complex IV deficiency in which a novel pathogenic homozygous nonsense variant was detected in COX16 by whole‐exome sequencing (WES)." (PMID 33169484, 2021).
oral squamous cell carcinoma (1 paper, 2025). "In oral squamous cell carcinoma, DAZAP1 regulates the splicing of cytochrome c oxidase 16 (COX16) pre-mRNA, boosting COX16 expression to enhance mitochondrial respiration and promote tumor progression." (PMID 40401521, 2025).
tumor (4 papers, 2020 to 2026). "When survival of HPV+ HNSCC patients with low expression of both COX16 and COX17 in their tumours was compared to survival of patients with high expression of both genes, survival was significantly greater in the COX16 and COX17 double low expression group (p = 0.0015)." (PMID 31968678, 2020). "Importantly, however, the interrogation of the DEPC 3.0 database showed that nearly all of the identified proteins, with the exception of only three (COX16, NDUFB2, COX8C), are consistently annotated as being altered during tumor dissemination and metastatic progression." (PMID 41157129, 2025).
blood cancer (1 paper, 2023). "Among them, HPRT1, TSC22D1, and COX16 have significantly correlated dependence profiles (p < 0.05) with PRDM15 in lymphocyte or blood cancer cell lines from these pathways." (PMID 36674842, 2023).
mitochondrial disease (1 paper, 2021). "Our data provide clear evidence for the pathogenicity of the COX16 variant as a cause for the observed clinical features and the isolated complex IV deficiency in these two patients and that COX16 deficiency is a cause for mitochondrial disease." (PMID 33169484, 2021). "Our data demonstrate that COX16 deficiency is a cause of mitochondrial disease." (PMID 33169484, 2021).
COX16 also shares sentences with these, for which no sentence is quoted: bone cancer (1 paper); cancer (1); cardiomyopathy (1); encephalomyopathies (1); lactic acidosis (1); liver dysfunction (1); Stillbirth (1).